LAMTOR5-AS1 (LAMTOR5 and SLC16A4 antisense RNA 1)
Synonyms: SLC16A4-AS1
Gene: Long non-coding RNA gene on chromosome 1 (110,347,116 to 110,443,817, forward strand). Ensembl gene ENSG00000224699.
Diseases named in the same sentence as LAMTOR5-AS1 in open-access papers:
LAMTOR5-AS1 is named in the same sentence as 2 diseases in open-access papers, as found by Europe PMC text mining. Sharing a sentence is not in itself a finding about the gene and the disease. The quoted sentences say what the papers report.
non-small cell lung carcinoma (1 paper, 2021). A group of at least three distinct histological types of lung cancer, including non-small cell squamous cell carcinoma, adenocarcinoma, and large cell carcinoma. "Long-noncoding RNA LAMTOR5 antisense RNA 1 (LAMTOR5-AS1) has been certified as a risk predictor and diagnostic biomarker of prostate cancer and non-small cell lung cancer." (PMID 34862368, 2021).
LAMTOR5-AS1 also shares sentences with these, for which no sentence is quoted: prostate carcinoma (1 paper).